HOMER1 (homer scaffold protein 1)
Diseases named in the same sentence as HOMER1 in open-access papers (continued):
Sharing a sentence is not in itself a finding about the gene and the disease.
Angelman syndrome (1 paper, 2016). A neurogenetic disorder characterized by severe intellectual deficit and distinct facial dysmorphic features. "Interestingly, a different study found an increased interaction of mGluR5 to the long isoform of Homer1, and it was found that this increased interaction also enhanced mGluR5-dependent LTD in an Angelman syndrome mouse model." (PMID 26929812, 2016).
atherosclerosis (1 paper, 2014). A disease characterized by the build-up of fatty material and calcium deposition in the arterial wall resulting in partial or complete occlusion of the arterial lumen. "While whether there is a correlation between cIMT and Homer1, or whether the combination of cIMT and Homer1 could be a more useful diagnostic method for early atherosclerosis still need further studies." (PMID 25551602, 2014). "In our study, Homer1, like TNF-α and IL-1β, could be a potential and important participant in diagnosing early atherosclerosis, consequently, CAD." (PMID 25551602, 2014). "Since Homer’s important role in platelet’s activation and the gene expression of Homer1 has some relevance with CAD in the present study, we may suppose that Homer1 is an important participant in early atherosclerosis, consequently, CAD." (PMID 25551602, 2014).
bladder tumors (1 paper, 2022). "Herein, our team discovered that the expression of Homer-1 was high in bladder tumors and negatively correlated with patient OS." (PMID 36211359, 2022).
cerebral infarction (1 paper, 2024). An ischemic condition of the brain, producing a persistent focal neurological deficit in the area of distribution of the cerebral arteries. "Homer1 knockdown resulted in the aggravation of neuronal necroptosis and inflammatory reactions, enlargement of the cerebral infarction area, and further aggravation of neurological deficit symptoms in mice." (PMID 38091015, 2024). "In this study, stereotaxic injection of Homer1 into the middle cerebral artery blood supply area of mice showed that Homer1 significantly diminished cell death and neuroinflammation, reduced the cerebral infarction area, and ameliorated the symptoms of neurological deficits in mice." (PMID 38091015, 2024).
cognitive decline (1 paper, 2021). "Other side-effects such as cognitive decline, visual hallucinations and daytime sleepiness have been implicated in various polymorphisms of the COMT, DRD2, DRD3, HOMER1 and BDNF genes, but lack consistency in the results to consider current clinical implementations." (PMID 34281267, 2021).
deafness (1 paper, 2021). An inherited or acquired condition characterized by the complete loss of the ability to hear from one or both ears. "Moreover, a previous study revealed that Homer1 has the same regulatory elements with miR-96 and miR-1271, and the mutation of miR-96 and miR-1271 leads to deafness in humans and mice, which indicates the close association between Homer1 and hearing-related disease." (PMID 34546852, 2021).
Duchenne muscular dystrophy (1 paper, 2011). Duchenne muscular dystrophy (DMD) is a neuromuscular disease characterized by rapidly progressive muscle weakness and wasting due to degeneration of skeletal, smooth and cardiac muscle. "Since loss of Homer 1 isoforms has been shown to result in TRP channel dysregulation in skeletal muscle, oxidative modification of Homer scaffolds may also provide a link between oxidative stress and dysregulation of TRP channel activity such as that observed in Duchenne's muscular dystrophy." (PMID 22043307, 2011).
hemorrhage (1 paper, 2022). Loss of blood from the vascular compartment to the exterior or into nonvascular body space as a result of rupture or severance of the blood vessels. "Finally, Homer1 protein and selumetinib were injected into in situ hemorrhage sites in the brains of Homer1flox/flox/Nestin-Cre+/− mice to study the efficacy of Homer1 in the treatment of ICH by using a mouse cytokine array to explore the potential mechanism." (PMID 35287697, 2022).
hemorrhagic stroke (1 paper, 2021). A stroke caused by a bleed on the brain. "However, 14 days after hemorrhagic stroke, both SYP+ and Homer-1+ proteins were engulfed by microglia/macrophages but few were engulfed by astrocytes." (PMID 34836962, 2021). "Similarly, 14 days after hemorrhagic stroke, microglia/macrophage-specific MEGF10KO or MERTKKO mice also exhibited fewer Homer-1+ and SYP+ synaptic puncta in microglia/macrophages than control mice." (PMID 34836962, 2021).
heroin addicts (1 paper, 2013). "Opioids and their withdrawal alter Homer1 gene products within the PFC and AMY and recently, polymorphisms in Homer1, as well as changes in striatal and AMY Homer1 mRNA expression, were reported in post-mortem studies of heroin addicts." (PMID 23761764, 2013).
insomnia (1 paper, 2020). A sleep disorder characterized by difficulty in falling asleep and/or remaining asleep. "Nevertheless, when considering the physiological mechanisms related to glutamate neurotransmission and previous associations with sleep, HOMER1 sounds like a good candidate gene for sleep phenotypes related to extended wake like insomnia." (PMID 32645048, 2020). "In that way, we may cautionary propose the SNP described here could mediates the integration Homer1/mGluR5 through 3’UTR mechanisms cited above, and therefore would mediates a compensatory mechanism to promote wakefulness in the sleep-deprived state like insomnia states." (PMID 32645048, 2020).
lung carcinoma (1 paper, 2025). "It was shown that after SeV infection, there was an increase in the biosynthesis of circHOMER1, while there was a decrease in the linear transcript HOMER1 and the pre-mRNA in both HEK293T and lung cancer epithelial cell lines." (PMID 40662732, 2025).
muscular atrophy (1 paper, 2025). The loss of muscle tissue due to inactivity or disease. "Within this pathway, HOMER1 regulates myofiber differentiation, HOMER2 associates with microgravity-induced muscular atrophy, and ADCY9-mediated cAMP signaling maintains muscle mass and function." (PMID 41153960, 2025).
myocardial ischemia (1 paper, 2021). A disorder of cardiac function caused by insufficient blood flow to the muscle tissue of the heart. "Our previous studies demonstrated that Homer1 protects cardiomyocytes against myocardial ischemia induced injury, and we further demonstrated that Homer1 protects cardiomyocytes against I/R injury." (PMID 33535171, 2021).
occlusive arterial disease (1 paper, 2017). "In conclusion, Homer1 downregulation can be considered for future therapeutic treatment of occlusive arterial disease." (PMID 28698564, 2017). "We have demonstrated that downregulation of Homer1 acts as a protective mechanism against neointima formation and occlusive arterial disease." (PMID 28698564, 2017). "Taken together, these data indicate the significance of Homer1 in occlusive arterial disease." (PMID 28698564, 2017).
osteoporosis (1 paper, 2025). A condition of reduced bone mass, with decreased cortical thickness and a decrease in the number and size of the trabeculae of cancellous bone (but normal chemical composition), resulting in increased fracture incidence. "In conclusion, CaSR enhances OB differentiation, likely via Homer1-mediated regulation of AKT signaling, suggesting CaSR as a potential therapeutic target for osteoporosis." (PMID 40059879, 2025).
prion disease (1 paper, 2012). A transmissible disease that is caused by a protein that is able to induce abnormal folding of normal cellular proteins, leading to characteristic spongiform brain changes, which are associated with neuronal loss without an inflammatory response. "We validated the early over-expression of HOMER1, another gene that is induced by synaptic activity and a novel finding in prion disease." (PMID 23144617, 2012).
Sepsis (1 paper, 2023). Sepsis is defined as life-threatening organ dysfunction caused by a dysregulated host response to infection. "High-resolution three-dimensional (3D) Airyscan imaging revealed enhanced engulfment of synapses (Homer1) in microglia at the acute and post-acute state on days 3 and 10 but no increase at day 38 following sepsis induction." (PMID 37235660, 2023).
Skeletal myopathy (1 paper, 2021). "Homer 1 is either diffusely distributed at the I band with reinforcement of the Z line or localises to the Z-disk; transgenic Homer 1-/- mice exhibit a skeletal myopathy characterised by abnormal TRP channel activity." (PMID 34564458, 2021).
tauopathy (1 paper, 2024). Neurodegenerative disorders involving deposition of abnormal tau protein isoforms (tau proteins) in neurons and glial cells in the brain. "Given that synaptic loss is a feature of tauopathy that is also presented in Tau22 mice, we performed immunofluorescence staining of synapses at the CA1 region using VGLUT1 and Homer1 as presynaptic and postsynaptic markers, respectively." (PMID 37988169, 2024).
Tinnitus (1 paper, 2021). Tinnitus is an auditory perception that can be described as the experience of sound, in the ear or in the head, in the absence of external acoustic stimulation. "Tinnitus can be caused by noise, and Homer1 was reported to be significantly downregulated in the ventral cochlear nucleus of mice 2 days after exposure to noise." (PMID 34546852, 2021). "Considering the close relationship between tinnitus and attention, emotion, memory, perception functions, we hypothesized that Homer1 is associated with tinnitus." (PMID 34546852, 2021). "Our findings only provided the primary evidence for the expression of Homer1 in sodium salicylate-induced tinnitus in mice, while experiments using neurons are needed to confirm the results." (PMID 34546852, 2021). "Effects of two inhibitors of metabolic glutamate receptor 5 (mGluR5), noncompetitive 2-Methyl-6-(phenylethynyl)-pyridine (MPEP) and competitive α-methyl-4-carboxyphenylglycine (MCPG), on the tinnitus scores of the mice and on Homer1 expression were detected." (PMID 34546852, 2021). "Our findings innovatively demonstrated that Homer1 is upregulated in the auditory cortex of mice with salicylate-induced tinnitus." (PMID 34546852, 2021). "MPEP significantly reduced tinnitus scores and suppressed Homer1 expression in a concentration dependent manner." (PMID 34546852, 2021). "The effects of two mGluR5 inhibitors, MPEP and MCPG, on tinnitus scores and on expression of Homer1 were subsequently investigated." (PMID 34546852, 2021). "Our findings could contribute to further understanding of pathophysiology and therapy of tinnitus, while more studies are needed to reveal the detailed mechanisms linking Homer1 and tinnitus in the future." (PMID 34546852, 2021). "We found that Homer1 expression was upregulated in the auditory cortex of mice with tinnitus, while expression of Homer2 or Homer3 exhibited no significant alteration." (PMID 34546852, 2021). "In conclusion, Homer1 expression was upregulated in the auditory cortex of mice after tinnitus, and was suppressed by noncompetitive mGluR5 inhibitor MPEP, but not competitive mGluR5 inhibitor MCPG." (PMID 34546852, 2021).
Zinc deficiency (1 paper, 2021). A deficiency of the essential metal Zinc; an essential cofactor for many enzymes. "In line with this hypothesis, we found that chronic zinc deficiency affects only a specific pool of synaptic ZIP4 proteins found at synapses with high HOMER1 levels, likely the pool of mature synapses." (PMID 33925953, 2021).
neurological diseases (12 papers, 2012 to 2025). "Homer1, a postsynaptic density protein, is a key regulator of neuronal synaptic activity and neurological disease pathogenesis." (PMID 36763283, 2023). "Among the top 50 database-predicted targeted genes, 8 genes (HOMER1, FRAT2, GRM5, TGFBR1, KDM3A, RGS2, ARRB1, and YWHAZ) were reported to be associated with axonal/neuronal regeneration/or neurological diseases." (PMID 36959678, 2023). "Importantly, the expression of genes related to synaptic plasticity and neurological diseases such as Arc, Homer1, and Itpr1 in the TgL group were significantly upregulated compared with the TgW group." (PMID 40420177, 2025).
psychiatric disorder (9 papers, 2014 to 2025). A disorder characterized by behavioral and/or psychological abnormalities, often accompanied by physical symptoms. "Homer1 activity has been shown to influence the functioning of other proteins and protein complexes linked to psychiatric disorders through genetic variants, such as FMRP, CYFIP1, Arc, SHANK, and the calcium channel Cav1.2." (PMID 29238619, 2017). "In conclusion, this study suggested that the HOMER1 rs2290639 was significantly associated with susceptibility to SA in Chinese affected by psychiatric disorders." (PMID 27386253, 2016). "Taken together, it is reasonable to conclude that HOMER1 rs2290639 was significantly associated with susceptibility to SA in both Caucasians and Chinese affected by psychiatric disorders." (PMID 27386253, 2016). "In the PFC, decreased expression was observed for Homer1, which plays a crucial role in the postsynaptic density of excitatory synapses, and Tanc2, which helps maintain synaptic structure and function and has been implicated in psychiatric disorders." (PMID 41002437, 2025). "Furthermore, mutations in HOMER1 have also been associated with other psychiatric disorders including autism." (PMID 29238619, 2017). "The HOMER1 rs2290639 polymorphism was significantly associated with susceptibility to SA in Hong Kong Chinese affected by psychiatric disorders, which might be explained by the potentially functional role of this polymorphism." (PMID 27386253, 2016). "Although there are several lines of evidence supporting the association of HOMER1 polymorphisms with psychiatric disorders or suicidal behavior in Caucasians, the results may be significantly different in other ethnic populations due to the widely reported genetic heterogeneity." (PMID 27386253, 2016). "Among the 36 duplicated genes, CMYA5, HOMER1, SERINC5 and RasGRF2 genes have been repeatedly associated with SCZ and other psychiatric disorders." (PMID 34946848, 2021). "Ankyrin-G and Homer1 have emerged as candidate genes in multiple psychiatric disorders including BD, SZ, and ASDs." (PMID 33398084, 2021). "Postmortem analyses show that Homer1 protein levels are altered in patients with psychiatric disorders." (PMID 29238619, 2017). "Previous work involving the knockout of Homer1 and GluN1 has elucidated their roles in learning and psychiatric disorders, leading us to speculate that their downregulation may contribute to T1D‐related disturbances in synaptic plasticity and memory." (PMID 37078449, 2023). "Furthermore, we report that circHomer1a, which is generated from the backsplicing of four exons from the psychiatric disorder-related, synaptically expressed HOMER1, is also significantly downregulated in iPS cell-derived neuronal cultures from SCZ and BD patients and the DLPFC of subjects with SCZ." (PMID 31988434, 2020).
infection (7 papers, 2012 to 2025). The state of being infected such as from the introduction of a foreign agent such as serum, vaccine, antigenic substance or organism. "At 10 days post-infection CHNs were subjected to IF-ICC with an anti-Homer1 mAb and an antibody against the dendritic marker MAP2." (PMID 31566565, 2019). "We also used qRT-PCR to validate the pre-clinical over-expression of 4 of these genes previously unrecognized as playing a role in prion pathobiology; RASGRF2, TRIB1, MCL1 and HOMER1 were all confirmed to be up-regulated during the same time period post-infection in CA1 pyramidal neurons." (PMID 23144617, 2012).
cancer (6 papers, 2019 to 2025). A tumor composed of atypical neoplastic, often pleomorphic cells that invade other tissues. "First, in co-cultures of SCLC cells and cortical neurons, immunostaining for glutamatergic vesicles (anti-VGluT1) and the postsynaptic protein HOMER1 revealed co-localizing formations at the contacts between neurons and cancer cells." (PMID 40931078, 2025). "Second, we identified similar contacts in co-cultures with human induced pluripotent stem (iPS) cell-derived cortical neurons, which were characterized by expression of the presynaptic protein Bassoon in neurons and HOMER1 in cancer cells." (PMID 40931078, 2025). "Lastly, we detected HOMER1–VGluT1 proximity at the interface of Cre-exposed, recombined eGFP-positive cancer cells in lung sections from autochthonous RP mice." (PMID 40931078, 2025). "Three-dimensional (3D) reconstruction of cortical neuron co-cultures showed a spatial organization consistent with synaptic structures, with VGluT1-positive puncta outside cancer cells juxtaposed to HOMER1 immunoreactivity in cancer cells." (PMID 40931078, 2025). "Fourth, we detected HOMER1-positive postsynaptic structures in cancer cells in close proximity to eGFP-positive axonal boutons in brain allografts." (PMID 40931078, 2025). "Here we also detected co-localization of presynaptic VGluT1 and postsynaptic HOMER1 in cancer cells, suggesting that synapses may also form in this primary setting." (PMID 40931078, 2025). "However, the role of Homer-1 in cancer immunotherapy is unclear." (PMID 36211359, 2022). "We further analyzed the differential expression of DPYSL4, HOMER1, ABCB6, CENPA, CDK1, STMN1 in cancer and adjacent tissues, and found that compared with adjacent tissues, the six genes in 309 HCC tissues were significantly up-regulated (P<0.01)." (PMID 31790363, 2019).
neurodevelopmental disorder (5 papers, 2021 to 2025). A behavioral and cognitive disorder with onset during the developmental period that involves impaired or aberrant development of intellectual, motor, or social functions. "Potentially damaging CNVs (pdCNVs) provided support to the involvement of inherited variants in PHF3, NEGR1, TIAM1 and HOMER1 in neurodevelopmental disorders (NDD), although mostly acting as susceptibility factors with incomplete penetrance." (PMID 37961520, 2023). "Our proteomic data suggests that Homer1 is important for the maintenance of synaptic PPI networks, and its loss results primarily in the upregulation of synaptic abundance of postsynaptic and neurodevelopmental disorder-related proteins." (PMID 33398084, 2021). "Taken together, our data suggest that Homer1 is important for the maintenance of synaptic PPI networks, and its loss results primarily in the upregulation of synaptic abundance of postsynaptic and neurodevelopmental disorder-related proteins." (PMID 33398084, 2021).
tumor (5 papers, 2019 to 2024). "Experimental validation in LUAD cells revealed that HOMER1 can inhibit tumor cell proliferation, migration, and invasion." (PMID 39445019, 2024). "In addition to several reported eEF2K-interacting proteins like eEF235 and Homer1,36 GSK3β, a key regulator of tumor immunity by inducing phosphorylation-dependent PD-L1 proteasomal degradation, was shown to be a potential partner of eEF2K." (PMID 35347072, 2022).
cardiovascular disease (2 papers, 2021 to 2022). "The involvement of Homer1 in some cardiovascular disease conditions has been demonstrated in our and previous studies." (PMID 33535171, 2021). "Another study suggested that the expression level of Homer1 in peripheral blood leukocytes of patients with CHD is closely related to the occurrence and development of cardiovascular diseases, and may have certain diagnostic value for CHD." (PMID 35546659, 2022).
myopathy (2 papers, 2020 to 2022). A disease of the muscle in which the muscle fibers do not function properly. "Experiments with Homer 1 knockout in mice caused myopathy, most likely caused by a dysregulation of TRP channel activity leading to a disrupted Ca2+ homeostasis." (PMID 36499379, 2022). "TRPC1 binds to Homer 1, and mice lacking Homer 1 exhibit myopathy characterized by decreases in muscle fiber cross-sectional area and force generation due to constitutive Ca2+ entry thorough TRPC1 (as an SAC)." (PMID 32244622, 2020).